LIPK (lipase family member K)
Description:
Plays a highly specific role in the last step of keratinocyte differentiation. May have an essential function in lipid metabolism of the most differentiated epidermal layers.
Synonyms: LIPL2; bA186O14.2
Tractability: Small molecule: it belongs to a druggable protein family. Antibody: UniProt places it where antibodies can reach, with high confidence; its Gene Ontology location is reachable by antibodies, with high confidence; UniProt predicts a signal peptide or a membrane-spanning region.
Gene: Protein-coding gene on chromosome 10 (88,706,249 to 88,752,776, forward strand). Ensembl gene ENSG00000204021.
Subcellular location: Secreted
Pathways (Reactome):
Developmental Biology: Formation of the cornified envelope
Gene Ontology:
Molecular function: lipoprotein lipase activity; carboxylic ester hydrolase activity; hydrolase activity, acting on ester bonds; lipase activity
Biological process: cornification; lipid metabolic process
Cellular component: extracellular region
Genetic constraint (gnomAD): Loss-of-function variants: 22 observed, 30.2 expected, observed/expected ratio (o/e) 0.73, 90% interval 0.52 to 1.04. The upper end of that interval is the gene's LOEUF score, 1.04, which puts it in group 4 of 6, group 1 being the genes least tolerant of losing a copy. Missense variants: 367 observed, 327.89 expected, observed/expected ratio (o/e) 1.12, 90% interval 1.03 to 1.22. Synonymous variants: 123 observed, 115.96 expected, observed/expected ratio (o/e) 1.06, 90% interval 0.92 to 1.23.
Homologues: Orthologues: chimpanzee LIPK (99% identical), macaque LIPK (96% identical), dog LIPK (83% identical), rabbit LIPK (81% identical), rat Lipk (81% identical), mouse Lipk (81% identical), guinea pig LIPK (78% identical), Caenorhabditis elegans lipl-1 (39% identical), Caenorhabditis elegans lipl-2 (39% identical), Caenorhabditis elegans lipl-6 (38% identical), Caenorhabditis elegans lipl-5 (38% identical), Caenorhabditis elegans lipl-3 (37% identical), and 23 more. Paralogues in human: LIPF (62% identical), LIPA (56% identical), LIPJ (54% identical), LIPM (53% identical), LIPN (50% identical).
Diseases named in the same sentence as LIPK in open-access papers:
LIPK is named in the same sentence as 7 diseases in open-access papers, as found by Europe PMC text mining. Sharing a sentence is not in itself a finding about the gene and the disease. The quoted sentences say what the papers report.
alcoholic liver diseases (1 paper, 2025). A disorder caused by damage to the liver parenchyma due to alcohol consumption. "LIPK codes for an acid lipase, lipase family member k, which has not previously been associated with alcoholic liver disease, but has been described as being expressed in human epidermal tissues and plays a role in the barrier function of differentiated keratinocytes." (PMID 40040391, 2025).
COVID-19 (1 paper, 2023). A disease caused by infection with severe acute respiratory syndrome coronavirus 2. "We also found that five proteins (Afamin, I-309, NKG2A, PRS57, LIPK) and patient age serve as a signature that separates patients with mild COVID-19 and patients with moderate/severe COVID-19 with an error rate of 1.77% (AUC = 0.9804)." (PMID 37985892, 2023).
fibrosis (1 paper, 2025). the formation of excess fibrous connective tissue in an organ or tissue in a reparative or reactive process. "Five variable multi-omics analysis provided more granular understanding of the core differences in expression between groups, with ELOVL2, LIPK, LAMA3, and lncRNAs partnered with UHRF1BP1L and S1PR1 found to most reliably discriminate the control and fibrosis groups." (PMID 40040391, 2025).
lung adenocarcinoma (1 paper, 2025). A carcinoma that arises from the lung and is characterized by the presence of malignant glandular epithelial cells. "There is still a lack of systematic exploration regarding the specific targets of LIPK in lung adenocarcinoma, the mechanisms of epigenetic regulation, and its feasibility as a target for metabolic therapy." (PMID 40568599, 2025). "In recent years, several studies have suggested that genes such as SPRR1B, MFI2, LIPK, GREB1L, and GPR115 may play a potential role in lung adenocarcinoma (LUAD)." (PMID 40568599, 2025).
tumor (1 paper, 2025). "PCR results showed elevated expression of GREB1L, MFI2, SPRR1B, GPR115 and LIPK mRNA in LUAD tumor tissues." (PMID 40568599, 2025).
LIPK also shares sentences with these, for which no sentence is quoted: infection (3 papers); ovarian carcinoma (1).